RNU4-71P (RNA, U4 small nuclear 71, pseudogene)
Gene: Small nuclear RNA gene on chromosome 8 (23,600,026 to 23,600,138, reverse strand). Ensembl gene ENSG00000252067.
Homologues: Orthologues: chimpanzee U4 (97% identical), guinea pig U4 (58% identical), pig U4 (57% identical). Paralogues in human: RNU4-30P (65% identical), RNU4-67P (65% identical), RNU4-36P (64% identical), RNU4-72P (64% identical), RNU4-49P (63% identical), RNU4-53P (63% identical), RNU4-59P (63% identical), RNU4-28P (62% identical), RNU4-24P (61% identical), RNU4-77P (61% identical), RNU4-51P (60% identical), RNU4-90P (60% identical), and 82 more.